SENP3 (SUMO specific peptidase 3)
Diseases named in the same sentence as SENP3 in open-access papers (continued):
Sharing a sentence is not in itself a finding about the gene and the disease.
ovarian carcinoma (4 papers, 2015 to 2022). A malignant neoplasm originating from the surface ovarian epithelium. "The goal of the current study was to examine single nucleotide polymorphisms (SNPs) in circadian genes BMAL1, CRY2, CSNK1E, NPAS2, PER3, REV1 and TIMELESS and downstream transcription factors KLF10 and SENP3 as predictors of risk of epithelial ovarian cancer (EOC) and histopathologic subtypes." (PMID 26807442, 2015). "In the formation and development of various cancers, SENP3 has been found to play an essential role, such as head and neck cancer, ovarian cancer and oral squamous cell cancer." (PMID 36698419, 2022). "It was verified that SENP3 promoted cell proliferation, metastasis, and tumorigenesis in ovarian cancers as a redox-sensitive molecule mediating EMT in ovarian cancer cells." (PMID 33192553, 2020). "When SENP3 was knocked down, the proliferation, metastasis, and invasion of ovarian cancer cells were greatly weakened, and the expression levels of proliferating cell nuclear antigen (PCNA), FOXC2, and neuronal cadherin (N-cadherin) were decreased." (PMID 33192553, 2020). "SENP3 expression is increased in ovarian cancer compared with that in normal tissues." (PMID 33192553, 2020). "Therefore, SENP3 might play a critical role in the progression of epithelial ovarian cancer, and SENP3 could serve as a potential biomarker for the prognosis of ovarian cancer." (PMID 33192553, 2020). "Ultimately, the regulation of SENP3 may provide a promising therapeutic target for ovarian cancer." (PMID 33192553, 2020).
pancreatic cancer (4 papers, 2022 to 2025). "Among de-SUMOylating enzymes, SENP3 has been most extensively studied, reflecting its critical role in pancreatic cancer—and its function is dual-faceted." (PMID 41463025, 2025). "The elapsed pancreatic cancer samples from TCGA data show that SENP3 expression is a positive correlation factor with the survival time of patients." (PMID 35869062, 2022). "Clearly, SENP3 promotes pancreatic cancer cell survival under hypoxia while inhibiting metastasis; its dual oncogenic and tumour-suppressive roles remain unclear and warrant further investigation." (PMID 41463025, 2025). "Interestingly, the Gene Sets Enrichment Assay (GSEA) shows that most of top upregulated gene sets in SENP3 high vs. SENP3 low are related to inflammation and immune response, which are enriched in SENP3 high tumor samples from the pancreatic cancer patients with chemotherapy." (PMID 35869062, 2022). "Interestingly, we find a significant correlation between SENP3 expression level and prognosis in pancreatic cancer patients but not in other tumors like non-small cell lung cancer and triple-negative breast cancer patients (data not shown)." (PMID 35869062, 2022).
atherosclerosis (3 papers, 2025). A disease characterized by the build-up of fatty material and calcium deposition in the arterial wall resulting in partial or complete occlusion of the arterial lumen. "The enhanced synthetic phenotype driven by the SUMOylation-deficient mutant highlights the importance of SENP3-dependent deSUMOylation in fully activating KLF4-mediated phenotypic switching during atherosclerosis." (PMID 41307849, 2025). "A limitation of the present study is that only the ApoE−/− mouse model was employed to investigate the role of SENP3-mediated DeSUMOylation of CCL17 in atherosclerosis." (PMID 41266856, 2025). "Although the redox-sensitive sentrin/Small Ubiquitin-like Modifier (SUMO)-specific protease 3 (SENP3), which preferentially deconjugates SUMO2/3, has been linked to oxidative stress, its role in atherosclerosis remains poorly defined." (PMID 41307849, 2025). "To investigate the role of SENP3 in atherosclerosis, we first assessed its expression pattern under pro-atherogenic conditions." (PMID 41307849, 2025). "Our study also found that SENP3 exacerbates atherosclerosis through a novel mechanism involving the deSUMOylation of CCL17." (PMID 41266856, 2025). "Using smooth muscle-specific Senp3 knockout mice on an ApoE−/− background, we demonstrated that Senp3 deletion attenuates atherosclerosis, promotes plaque stability, and preserves the contractile VSMCs phenotype." (PMID 41307849, 2025). "To define the role of SENP3 in atherosclerosis, we generated Senp3flox/flox;Tagln-Cre mice on an ApoE−/− background, enabling SMC-specific Senp3 knockout." (PMID 41307849, 2025). "Although prior studies have implicated SENP3 in cancer and metabolic cardiovascular diseases through substrates such as β-catenin, YAP1 and CTH, its role in atherosclerosis has not been explored." (PMID 41307849, 2025). "Together, these findings demonstrated that SENP3 is consistently upregulated in VSMCs under atherogenic conditions both animal models and cell culture systems, suggesting a potential role in VSMC phenotypic switching during atherosclerosis." (PMID 41307849, 2025). "In term of cardiovascular disease, SENP3 has been shown to be upregulated in atherosclerosis, where it stabilizes β-catenin protein through deSUMOylation, thereby promoting VSMC migration and aggravating atherosclerosis." (PMID 41266856, 2025). "SENP3 has been shown to be elevated in atherosclerosis, where it stabilizes β-catenin protein through desumoylation modification, promoting VMSC migration and exacerbating atherosclerosis." (PMID 41266856, 2025). "However, the potential regulation of KLF4 by SENP3, and functional consequences of such regulation in VSMCs and atherosclerosis, have not been explored." (PMID 41307849, 2025). "Notably, smooth muscle-specific deletion of Senp3 conferred substantial protection against atherosclerosis without major alterations in systemic lipid metabolism, indicating a vessel-autonomous mechanism." (PMID 41307849, 2025). "Thus, under atherogenic conditions, upregulation of SENP3 represents a critical mechanism that amplifies KLF4 signaling by preventing its degradation and fine-tuning its activity, thereby driving VSMCs plasticity and atherosclerosis progression." (PMID 41307849, 2025). "Although SENP3 has been implicated in cancer and metabolic disease through its deSUMOylation of substrates such as β-catenin, YAP1 and CTH, its potential role in atherosclerosis and VSMC phenotypic modulation has not been examined." (PMID 41307849, 2025). "Based on the established roles of SENP3 in regulating key signaling molecules and the critical function of KLF4 in VSMC biology, we hypothesize that SENP3 promotes VSMCs phenotypic switching and atherosclerosis progression through deSUMOylation and stabilizing KLF4." (PMID 41307849, 2025).
cardiac ischemia (3 papers, 2019 to 2024). "Indeed, SENP1, SENP2 and SENP5, as well as SENP3, have each been strongly implicated in cardiac ischemia/reperfusion so it is likely that distinct subsets of SUMOylated proteins are regulated by different SENPs." (PMID 30973885, 2019). "In mice with myocardial ischemia–reperfusion injury, upregulation of SENP3 expression in the heart is contingent upon ROS generation, consequently promoting Drp1 mitochondrial translocation." (PMID 38615367, 2024). "The study indicated that SENP3 contributes to myocardial ischemia-reperfusion injury in mice, which is in contrast to the results of previous studies." (PMID 33192553, 2020). "Together, our results indicate that cardiac ischemia dramatically alter levels of SENP3 and suggest that this may a mechanism to promote cell survival after ischemia-reperfusion in heart." (PMID 30973885, 2019).
laryngeal carcinoma (3 papers, 2020 to 2025). Carcinoma that arises from the laryngeal epithelium. "The activation of Nrf2 in laryngeal carcinoma is stimulated by cisplatin-induced ROS (reactive oxygen species) production through the deSUMOylation activity of SENP3." (PMID 33192553, 2020). "It was demonstrated that SENP3 protein levels are positively correlated with smoking and STAT3 Y705 phosphorylation levels in laryngeal carcinoma." (PMID 33192553, 2020).
melanoma (3 papers, 2014 to 2021). A malignant, usually aggressive tumor composed of atypical, neoplastic melanocytes. "We next examined the role of Treg cell-specific deletion of SENP3 in regulating antitumor responses in a B16-F10 melanoma model." (PMID 30089837, 2018). "B16-F10 mouse melanoma cells stably knocked-down or over-expressing SENP3 (B16-sh-SENP3, B16-SENP3) and the controls were injected into the mice." (PMID 25216525, 2014).
osteoporosis (3 papers, 2020 to 2025). A condition of reduced bone mass, with decreased cortical thickness and a decrease in the number and size of the trabeculae of cancellous bone (but normal chemical composition), resulting in increased fracture incidence. "We found that long-term use of GC can cause severe osteoporosis in mice but SENP3 +/− mice were less likely to suffer severe bone loss after GC induction; however, NAC injection might rescue the GIOP progress with eliminating Dex-induced ROS upregulation." (PMID 34249943, 2021). "However, the detailed molecular mechanism of SENP3 mediating osteoporosis has not been well studied." (PMID 40493284, 2025).
promyelocytic leukemia (3 papers, 2013 to 2025). "SENP3-mediated de-conjugation of SUMO2/3 from promyelocytic leukemia has been shown to correlate with accelerated cell proliferation under mild oxidative stress." (PMID 23467634, 2013).
prostate carcinoma (3 papers, 2013 to 2024). A carcinoma that arises from epithelial cells of the prostate gland. "In line with this, our research reveals that SENP3 can promote the transition of EMT in the metastatic process of prostate cancer." (PMID 39623295, 2024). "SENP3 expression is also increased in prostate cancer and other carcinomas including, ovarian, lung, rectal and colon carcinomas." (PMID 23467634, 2013). "This suggests that as prostate cancer progresses to advanced stages, SENP3 may play a critical role in driving the invasiveness of prostate cancer." (PMID 39623295, 2024). "Assessment of tissue from human prostate cancer patients indicates elevated mRNA levels of SENP1 and the SUMO2/3 deconjugating enzyme, SENP3." (PMID 27178176, 2016).
cataract (2 papers, 2020 to 2024). Partial or complete opacity of the crystalline lens of one or both eyes that decreases visual acuity and eventually results in blindness. "Additional studies investigating the sumoylation functions and the related mechanisms in cataract development and progression will help to understand the role of SENP3 in cataract susceptibility." (PMID 38984127, 2024). "Also, male cataract patients had higher levels of SENP3, SENP7, and SENP8 than female patients." (PMID 32827359, 2020).
esophageal squamous cell carcinoma (2 papers, 2023 to 2024). Esophageal squamous cell carcinoma (ESCC) is a type of esophageal carcinoma (EC) that can affect any part of the esophagus, but is usually located in the upper or middle third. "We further found that SENP3 in esophageal squamous cell carcinoma was mainly expressed in CD206+ macrophages." (PMID 39123188, 2024). "• SENP3 expression is upregulated in macrophages in esophageal squamous cell carcinoma." (PMID 39123188, 2024). "• The absence of SENP3 in macrophages promotes the progression of esophageal squamous cell carcinoma both in patients and in the 4-NQO-induced ESCC mice model." (PMID 39123188, 2024).
glioma (2 papers, 2020 to 2022). A benign or malignant brain and spinal cord tumor that arises from glial cells (astrocytes, oligodendrocytes, ependymal cells). "Sp3 is functionally regulated by SUMOylation, and SENP3 mediates the deSUMOylation of Sp3 in glioma." (PMID 33192553, 2020).
head and neck cancer (2 papers, 2022). A primary or metastatic malignant neoplasm affecting the head and neck. "SENP3 positively regulates the activation of STAT3 by promoting deSUMOylation of STAT3 in head and neck cancer after the simulation of tobacco." (PMID 36227136, 2022).
lymph node metastasis (2 papers, 2014 to 2022). "SENP3 level showed a negative correlation (R < −0.6) with CD206 level in patients with advanced tumors (stage T3/T4, TNM grade III, and lymph node metastasis), whereas such a correlation was not seen in lower‐grade tumors." (PMID 33932085, 2022).
Obesity (2 papers, 2023 to 2024). Accumulation of substantial excess body fat. "In this present study, we highlight the critical role of SUMO-specific protease 3 (SENP3) in the pathogenesis of obesity and obesity-associated inflammation." (PMID 38070059, 2023). "We found that SENP3 protein levels were markedly increased after exposure to associated stimuli relevant to obesity, both in vivo and in vitro." (PMID 38070059, 2023). "Most importantly, SENP3 deficiency reduces YAP1 protein level in adipose tissue during obesity." (PMID 38070059, 2023). "Therefore, SENP3 deficiency in macrophage protects mice against diet-induced obesity." (PMID 38070059, 2023). "During high-fat diet (HFD)-induced obesity in mice, SENP3 expression in adipose tissue macrophages (ATMs) is significantly increased, while myeloid-specific SENP3 deficiency protects mice from HFD-induced obesity and systemic inflammation." (PMID 39431155, 2024). "To further define the in vivo role of SENP3 in YAP1 signaling and obesity, we investigated the in vivo expression of SENP3 and YAP1 in adipose tissue of Senp3flox/flox; Lyz2-Cre mice and Senp3flox/flox littermates." (PMID 38070059, 2023). "However, the role of SENP3 in obesity-associated inflammation remains largely unknown." (PMID 38070059, 2023). "To further investigate the role of SENP3 expressed by macrophage in age-induced obesity, we followed up Senp3flox/flox; Lyz2-Cre mice and Senp3flox/flox littermates until they are almost 18 month old." (PMID 38070059, 2023). "In summary, we provided the first evidence that SENP3 accumulates in ATMs of adipose tissue during diet and age-induced obesity, which promotes macrophage infiltration in adipose tissue and systemic inflammation via regulation of YAP1 SUMOylation." (PMID 38070059, 2023). "Consistently, we found that myeloid-specific SENP3 deletion reduces serum levels of inflammatory factors during age-induced obesity." (PMID 38070059, 2023). "To investigate the functional importance of SENP3 expressed by macrophage during obesity, we generated the mice with myeloid-specific SENP3 deletion by intercrossing Senp3flox/flox mice with Lyz2-Cre mice." (PMID 38070059, 2023). "To better understand the effects of SENP3 on adipose tissue macrophage (ATM) activation and function within the context of obesity, we generated mice with myeloid-specific deletion of SENP3 (Senp3flox/flox;Lyz2-Cre mice)." (PMID 38070059, 2023). "In this present study, we assessed the expression and function of macrophage SENP3 in adipose tissue during obesity; we also examined the SUMO modification of YAP1." (PMID 38070059, 2023). "Our findings demonstrate that SENP3 is essential for ATMs activation and function during the context of obesity." (PMID 38070059, 2023). "To investigate the role of SENP3 in ATM function during obesity, we generated the mouse model of high-fat diet (HFD)-induced obesity and examined the expression of SENP3 in white adipose tissue." (PMID 38070059, 2023). "We found that the expression of SENP3 is dramatically increased in ATMs during high-fat diet (HFD)-induced obesity in mice." (PMID 38070059, 2023). "Myeloid-specific SENP3 deletion attenuates macrophage infiltration in adipose tissue and reduces serum levels of inflammatory factors during diet and age-induced obesity." (PMID 38070059, 2023). "Taken together, all these results suggest a potential role of macrophage SENP3 in the development of HFD-induced obesity." (PMID 38070059, 2023). "Taken together, all these results suggest SENP3 promotes ATM accumulation in adipose tissue and systemic inflammation during obesity." (PMID 38070059, 2023). "Our results highlight the important role of SENP3 in ATM inflammation and diet and age-induced obesity." (PMID 38070059, 2023). "Further work is needed to fully understand the exact role of SENP3 and SENP3-mediated SUMO/de-SUMOylation status of specific protein substrates in ATM during obesity and related comorbidities." (PMID 38070059, 2023).
Obesity (continued). "Myeloid-specific SENP3 deletion reduces adiposity, adipocyte size, and ATM infiltration in adipose tissue in the context of diet and age-induced obesity." (PMID 38070059, 2023). "In addition, myeloid-specific SENP3 deletion attenuated HFD and age-induced obesity and systemic inflammation, which was partially mediated by YAP1 SUMOylation change." (PMID 38070059, 2023). "However, the role of SENP3 in macrophage activation and function in the context of obesity has never been investigated." (PMID 38070059, 2023). "In the context of HFD-induced obesity in mice, SENP3 regulates the deSUMOylation of YAP1, while the absence of SENP3 can abolish the upregulation of YAP1 induced by IL-1β." (PMID 39431155, 2024).
preeclampsia (2 papers, 2017 to 2020). Preeclampsia is a hypertensive disorder of pregnancy that is characterized by new-onset hypertension with proteinuria presenting after 20 weeks of gestation, and depending on mild or severe forms may initially present with severe headache, visual disturbances, and hyperreflexia. "In preeclampsia, decreased FIH1 protein expression associated with impaired deSUMOylation by SENP3 and increased association with the ubiquitin ligase RNF4." (PMID 29371964, 2017). "Interestingly, immunoprecipitation of FIH1 followed by Western Blot analysis for SENP3 showed a marked disruption of FIH1 deSUMOylation by SENP3 in preeclampsia, relative to AMC placentae." (PMID 29371964, 2017). "In early-onset preeclampsia, both HIF1A and FIH1 deSUMOylation by SENP3 was significantly elevated in the human placenta, and this partly contributes to increased HIF1A activity and stability in physiological and pathological conditions." (PMID 33192553, 2020).
Sepsis (2 papers, 2020 to 2023). Sepsis is defined as life-threatening organ dysfunction caused by a dysregulated host response to infection. "In the model of LPS‐induced sepsis, SENP3 cKO mice exhibited less severe acute lung injury than SENP3 fl/fl mice." (PMID 32237051, 2020). "SENP3 then promotes JNK activation, leading to TF expression in these cells, thereby initiating the coagulation cascade and leading to sepsis‐induced ALI." (PMID 32237051, 2020). "To assess how a lack of myeloid SENP3 expression affected the severity of septic ALI, we used the same mouse model of LPS‐induced sepsis." (PMID 32237051, 2020).
acute kidney injury (1 paper, 2025). Sudden and sustained deterioration of the kidney function characterized by decreased glomerular filtration rate, increased serum creatinine or oliguria. "Analysis of SENP family expression in mouse kidney tissue revealed that the transcriptional levels of SENP3 and SENP5 were significantly elevated in IRI-induced acute kidney injury (IRI-AKI) mice." (PMID 41350286, 2025).